DHCR7 (7-dehydrocholesterol reductase)
Diseases named in the same sentence as DHCR7 in open-access papers (continued):
Sharing a sentence is not in itself a finding about the gene and the disease.
vitamin D deficiency (20 papers, 2013 to 2024). A nutritional condition produced by a deficiency of VITAMIN D in the diet, insufficient production of vitamin D in the skin, inadequate absorption of vitamin D from the diet, or abnormal conversion of vitamin D to its bioactive metabolites. "From another perspective, recent studies have pointed out to the association between genetic variants, such as of the variants in DHCR7 gene, and vitamin D deficiency." (PMID 39845452, 2024). "Wehr and colleagues found that related polymorphisms of the DHCR7 gene are associated with insulin resistance and vitamin D deficiency in PCOS." (PMID 36695944, 2023). "Findings from large GWAS of a European cohort have shown that the DHCR7 rs12785878 variant was associated with vitamin D insufficiency." (PMID 28415985, 2017). "Our results suggest that genetic variation in DHCR7 is the major adaptation affecting vitamin D metabolism in recent evolutionary history which helped early humans to avoid severe vitamin D deficiency and enabled them to inhabit areas further from the equator." (PMID 23837623, 2013). "Our study showed that the proportion of vitamin D deficiency was higher in the NH group than in controls, and rs12785878 (NADSYN1/DHCR7) and rs10877012 (CYP27B1) are correlated with NH risk and vitamin D deficiency." (PMID 37259065, 2023). "The study concluded that genetic variation at several loci—rs2282679 in GC, rs12785878 near DHCR7, rs10741657 in CYP2R1, and rs6013897 in CYP24A1—have a noticeably elevated risk of vitamin D insufficiency." (PMID 36672957, 2023). "Findings from the present study suggested that NADSYN1/DHCR7 rs12785878 TT genotypes and CYP27B1 rs10877012 GT genotypes were associated with decreased risk of vitamin D deficiency." (PMID 37259065, 2023). "In accordance to our findings, Zhu H. and colleagues revealed that participants with severe vitamin D deficiency (25(OH)D ≤25 nmol/l) showed a pattern of reduced methylation of CYP2R1, CYP24A1 and DHCR7 genes in comparison with controls (25(OH)D >75 nmol/L)." (PMID 36061943, 2022). "A recent Mendelian randomization study has also shown that polymorphisms in vitamin D-related genes, CYP2R1 [rs10741657] and DHCR7 [rs12785878], were associated with LBW suggesting a causal link between maternal vitamin D deficiency and neonatal birth weight." (PMID 32548071, 2020). "DHCR7 and CYP24A1 have the largest reported effect sizes for Vitamin D deficiency and were found using ET." (PMID 27042214, 2016). "There were associations among NH, vitamin D deficiency and NADSYN1/DHCR7 and CYP27B1 polymorphisms, TT genotype of rs12785878 and GT genotype of rs10877012 could reduce the risk of vitamin D deficiency and NH." (PMID 37259065, 2023). "Different variants in the loci of the genes responsible for the synthesis, hydroxylation, and transport of vitamin D (such as DHCR7, CYP2R1, CYP24A1, and GC), as well as VDR gene polymorphisms may also be associated with the risk of vitamin D deficiency." (PMID 33330279, 2020). "Recent genetic studies have associated vitamin D deficiency with several candidate genes including Cytochrome P450, family 2, R, (CYP2R1), the group-specific component gene (GC) and 7-dehydrocholesterol reductase/NAD synthetase 1 (DHCR7/NADSYN1)." (PMID 25405862, 2014). "Different variants in the loci of genes (such as DHCR7, CYP2R1, CYP24A1, and GC) that are responsible for vitamin D synthesis, hydroxylation, and transport, as well as VDR gene polymorphisms, may be associated with the risk of vitamin D deficiency." (PMID 33330279, 2020). "SNPs for DHCR7, CYP2R1 and GC-rs4588 genes were not statistically significantly associated to vitamin-D deficiency." (PMID 35256680, 2022). "In conclusion, our results suggest that DHCR7 rs12785878 T>C might be associated with risk of EOAD in the Chinese population, while other SNPs related to vitamin D insufficiency might not be." (PMID 33692822, 2021).
breast carcinoma (8 papers, 2015 to 2025). "Changes in expression or methylation of GC, NADSYN1/DHCR7, and the other candidate genes may have less pervasive biological effects, but our findings support the hypothesis that these vitamin D-related genes and proteins may interact with circulating vitamin D levels to influence breast cancer risk." (PMID 29996894, 2018). "The Oncomine database demonstrated that mRNA expression of DHCR7 was significantly higher in various human cancers, including colorectal cancer, bladder cancer, breast cancer, head and neck cancer, and ovarian cancer, when compared to corresponding normal tissues." (PMID 41198144, 2025). "The most upregulated proteins by SBP1 induction included DKK1 that inhibits WNT pathway, DHCR7 that controls cholesterol and Vitamin D synthesis, ANXA4 that inhibits NFkB pathway and IL-8, and AGPAT5 that inhibits breast cancer cell proliferation." (PMID 25974208, 2015). "Quite remarkably, the two genes upregulated in this module (DHCR7 and UBE2C) are two members of the EndoPredict assay, an RT-PCR assay for predicting response to endocrine treatment in ER+/HER2 − breast cancer." (PMID 25886003, 2015).
microcephaly (7 papers, 2009 to 2024). A congenital or acquired developmental disorder in which the circumference of the head is smaller than normal for the person's age and sex. "For instance, while DHCR7 mutations in humans causes SLOS with growth retardation, microcephaly, micrognathia, and cleft palate, Dhcr7 KO mice display a distinct cleft palate with less than 10% penetrance." (PMID 38438535, 2024). "Dhcr7−/− knockout (KO) mice presented microcephaly, accelerated bone formation, and thicker calvaria bones at birth with complete penetrance, and died within 1 day after birth." (PMID 31934493, 2020). "In addition, mutations of the DHCR7 gene in humans cause SLOS, which is characterized by multiple congenital anomalies, including microcephaly, developmental delay, typical facial appearance, and cardiac abnormalities." (PMID 38472233, 2024). "Mutations in DHCR7, encoding the penultimate enzyme in the pathway (downregulated 1.46-fold in Piezo1 KO brains) underlie Smith–Lemli–Opitz syndrome (SLOS), which includes symptoms of microcephaly, mental developmental delay, and hearing impairment." (PMID 36069933, 2022).
type 1 diabetes (6 papers, 2012 to 2023). "Of note, genetically variants in DHCR7 and CYP2R1 have previously been demonstrated to be associated with increased risk of type 1 diabetes." (PMID 31660975, 2019). "For example, SNPs in NAD synthetase 1/ 7-dehydrocholesterol reductase (NADSYN1/DHCR7) gene locus and SNPs in CYP27B1, CYP2R1 genes and have been associated with type 1 diabetes or with type 1 diabetes related autoantibodies." (PMID 28976992, 2017). "The aim of this study was to evaluate whether the DHCR7 rs12785878, GC rs2282679, CYP2R1 rs2060793 and CYP24A1 rs6013897 SNPs are associated with the susceptibility to type 1 diabetes in the Portuguese population." (PMID 32764491, 2020). "In 612 infants, we genotyped single nucleotide polymorphisms in vitamin D metabolism genes that relate with type 1 diabetes: rs10741657 and rs12794714 in CYP2R1, rs12785878 in DHCR7, and rs10877012 in CYP27B1." (PMID 37170809, 2023).
autism (5 papers, 2014 to 2025). Persistent deficits in social interaction and communication and interaction as well as a markedly restricted repertoire of activity and interest as well as repetitive patterns of behavior. "Rare mutations in other autism related genes such as CNTNAP2 and CHD8 are also associated with both autism and macrocephaly,while mutations in the risk genes AUTS2 and DHCR7 give rise to autism and microcephaly." (PMID 26076356, 2015). "However, studies have shown that DHCR7 pathogenic variants are rare among ASD patients, and isolated autism is not an indication for biochemical screening for SLOS." (PMID 40724921, 2025).
COVID-19 (5 papers, 2021 to 2023). A disease caused by infection with severe acute respiratory syndrome coronavirus 2. "Our results pointed out to DHCR7/NADSYN1 rs12785878 and CYP2R1 rs10741657 variants, both involved in vitamin D synthesis, as potential risk factors of severe COVID-19." (PMID 34150833, 2021). "Specific SNPs located in the genes GC, DHCR7/NADSYN1, and VDR were associated with the critical COVID-19 condition among patients." (PMID 34835935, 2021). "Results of our study showed association of DHCR7/NADSYN1 rs12785878 and CYP2R1 rs10741657 variants with severe form of COVID-19 in adult patients." (PMID 34150833, 2021).
developmental delay (5 papers, 2019 to 2025). "It is the first time to report variants in EFNB1, NAA10, DHCR7, LAMA1 and NFIX in Chinese intellectual disability/developmental delay patients and first report about variants in NAA10 and LAMA1 in affected individuals of Asian ancestry." (PMID 31088393, 2019). "For example, Smith–Lemli–Opitz syndrome (SLOS), an inborn error in cholesterol synthesis resulting from mutations in the 7-dehydrocholesterol reductase (DHCR7) gene, manifests as developmental delays, abnormal neural development, and atypical peripheral lipid metabolism." (PMID 38419654, 2024).
cervical cancer (4 papers, 2022 to 2025). A primary or metastatic malignant neoplasm involving the cervix. "It should be noticed that we also used the GEO cohort (GSE30760) to validate whether DHCR7 expression was associated with survival of cervical cancer." (PMID 36164611, 2022). "The results indicated that DHCR7 is overexpressed in the majority of cancers, with the exception of brain/CNS cancer, cervical cancer, melanoma, and prostate cancer." (PMID 41198144, 2025). "We investigated the relationship between DHCR7 expression and clinicopathological features of cervical cancer patients." (PMID 36164611, 2022). "Cox analysis revealed that DHCR7 was an independent prognostic factor in cervical cancer (P = 0.005)." (PMID 36164611, 2022). "Taken together, the current study highlighted the potential role of DHCR7 as a prognostic biomarker for cervical cancer." (PMID 36164611, 2022). "In summary, we found that DHCR7 was significantly upregulated in cervical cancers and was correlated with unfavorable outcomes." (PMID 36164611, 2022). "DHCR7 is a potential anticancer target to improve radiosensitivity and chemosensitivity in cervical cancer." (PMID 36164611, 2022). "Comparison of DHCR7 expression in cervical cancer patients with different clinicopathological features revealed that DHCR7 expression increased with advanced clinical stage (P = 0.004) and T stage (primary tumors) (P = 0.009)." (PMID 36164611, 2022). "Elevated DHCR7 expression in cervical carcinoma was correlated with poor clinicopathological features including advanced clinical stage, advanced T stage, and lymph node invasion." (PMID 36164611, 2022). "However, DHCR7 expression was found to be significantly lower in brain and CNS cancer, cervical cancer, melanoma, and prostate cancer." (PMID 41198144, 2025). "The Wilcoxon rank sum test was used to explore DHCR7 expression level in cervical cancer." (PMID 36164611, 2022). "The results suggested that DHCR7 may promote tumor development and progression via these pathways in cervical cancer." (PMID 36164611, 2022). "High DHCR7 expression may suppress the function of immune system in cervical cancer by reducing CTLs and T-cell infiltration." (PMID 36164611, 2022). "Furthermore, DHCR7-related biological pathways involved in cervical cancer were screened by gene set enrichment analysis (GSEA)." (PMID 36164611, 2022). "High DHCR7 levels may be a biomarker of poor prognosis for cervical cancer." (PMID 36164611, 2022). "Thus, we speculate that DHCR7 may affect cervical cancer development and progression by regulating the immune-related pathways." (PMID 36164611, 2022). "The expression pattern and prognostic value of DHCR7 in cervical cancer are unknown." (PMID 36164611, 2022). "DHCR7 may be a potential biomarker for poor survival in cervical cancer." (PMID 36164611, 2022).
developmental disability (4 papers, 2020 to 2023). Disorders in which there is a delay in development based on that expected for a given age level or stage of development. "SQLE has been linked to Rett syndrome pathogenesis, and mutations in DHCR7 result in a developmental disability known as Smith-Lemli-Lopiz Syndrome (SLOS, MIM 270400), which resembles SMS in some aspects." (PMID 36411275, 2022). "We base this view on the data from human genetic syndrome SLOS where mutations in DHCR7 affect CNS structure and function leading to developmental disabilities and autism." (PMID 33526772, 2021). "In addition, DHCEO is considered a biomarker of increased oxidative stress in SLOS, an intellectual and developmental disability arising from two mutant copies of the DHCR7 genes, biochemically characterized by elevation in 7-DHC." (PMID 32504050, 2020).
dyslipidemia (4 papers, 2013 to 2021). "The discovery of the deficiency of DHCR7 as a cause for the SLOS made this syndrome the first true metabolic syndrome of multiple congenital malformations." (PMID 29311971, 2017).
gastric cancer (4 papers, 2023 to 2025). A primary or metastatic malignant neoplasm involving the stomach. "DHCR7 has crucial functions in several malignant diseases such as gastric cancer and colorectal cancer." (PMID 37891677, 2023). "Knockdown of DHCR7 rescued the reduced proliferation of DGC cells due to overexpression of ESRP1, and also rescued the clone-forming ability of ESRP1 on gastric cancer cells." (PMID 40528239, 2025). "The rescue experiments proved that knockdown of DHCR7 could be restored the effect of ESRP1 overexpression on proliferation, migration, invasion and ferroptosis of gastric cancer cells, indicating that ESRP1 inhibits DGC progression by promoting DHCR7-mediated ferroptosis." (PMID 40528239, 2025).
hepatocellular carcinoma (4 papers, 2024 to 2026). A malignant tumor that arises from hepatocytes. "Another study indicates that DHCR7 contributes to M2 macrophage polarization in hepatocellular carcinoma, promoting tumor growth and metastasis." (PMID 40735323, 2025). "Ferroptosis in human hepatocellular carcinoma-derived cells was suppressed by genetic and pharmacological inhibition of DHCR7, and also by exogenous supplementation with the substrate for DHCR7, 7-dehydrocholesterol (7-DHC)." (PMID 38472233, 2024). "Transmembrane protein 147 (TMEM147) upregulates DHCR7 via signal transducer and activator of transcription 2 (STAT2) in hepatocellular carcinoma (HCC), elevating 27HC and GPX4, which strengthens ferroptosis resistance and metastasis." (PMID 41596341, 2026).
holoprosencephaly (4 papers, 2011 to 2025). Holoprosencephaly (HPE) is a complex brain malformation resulting from incomplete cleavage of the prosencephalon, occurring between the 18th and 28th day of gestation, and affecting both the forebrain and face, which results in neurological manifestations and facial anomalies of variable severity. "Other gene mutations that relates to holoprosencephaly, including ZIC2, SIX3, TGIF1, CDON, FGFR1, CENPF and DHCR7, were not identified." (PMID 39859210, 2025).
liver fibrosis (4 papers, 2013 to 2025). "The expression of the DHCR7 gene polymorphism has been shown to be associated with the severity of liver fibrosis." (PMID 28415985, 2017). "Furthermore, the combination of the detection of the DHCR7 rs12785878 variant with the severity of liver fibrosis or RVR increased the predictive value for SVR in HCV genotype 1 patients." (PMID 28415985, 2017). "Multivariate analysis of HCV genotype 1 patients showed that liver fibrosis stage 0–1 (OR = 5.00; 95% CI, 2.02–12.37; P < 0.001), and DHCR7 rs12785878 GT/TT allele (OR = 2.69; 95% CI, 1.03–7.05; P = 0.04) were independent pre-treatment predictors of SVR following PEG-IFN-based therapy." (PMID 28415985, 2017). "Univariate analysis of HCV genotype 1 patients showed that age, liver fibrosis stage 0–1, CYP27B1 rs10877012 polymorphism, and DHCR7 rs12785878 polymorphism were related to SVR." (PMID 28415985, 2017). "Moreover, it seems likely that DHCR7 inhibition can reduce the side effects on the liver in ferroptosis-inducing therapy against progressive liver fibrosis or chemotherapy-resistant cancers." (PMID 38472233, 2024). "DEN/chow-fed Dhcr7+/– and WT mice did not develop liver fibrosis." (PMID 40529212, 2025).
Obesity (4 papers, 2018 to 2021). Accumulation of substantial excess body fat. "A noteworthy intron variant is located in the vitamin D pathway gene DHCR7 (p-value 3.06 × 10−25), which has been associated with obesity traits in humans." (PMID 31296617, 2019). "Among those genes, the ACTN3 (Actinin alpha 3) constitutes an interesting candidate to regulate muscle performance through the calcineurin signalling and the DHCR7 gene (7-dehydrocholesterol reductase) associated with obesity through vitamin D pathway." (PMID 29522525, 2018). "The vitamin D synthesis-related genes, DHCR7 and CYP2R1, have not been adequately investigated in relation to obesity and T2D." (PMID 33553043, 2020).
ovarian carcinoma (4 papers, 2015 to 2026). A malignant neoplasm originating from the surface ovarian epithelium. "We found that suppression of SREBF2 in ovarian cancers results in down-regulation of cholesterogenic target genes such as the DHCR7, while induction of SREBF1 is associated with increased expression of lipid synthesis genes such as the SCD1, which was found highly elevated." (PMID 26807200, 2015). "We found that both SREBF2 and its target gene DHCR7 are downregulated in ovarian cancer tissues." (PMID 26807200, 2015). "To test this, we selected four ovarian cancer cell lines (OAW-42, OVCAR-8, ES-2, and EFO-21) of high molecular similarity to HGSOC tumors based on mutation, copy number and gene expression profiles for treatment with the DHCR7 inhibitor AY9944 (Datasets EV20 and 21)." (PMID 41233595, 2026).
Sepsis (4 papers, 2023 to 2024). Sepsis is defined as life-threatening organ dysfunction caused by a dysregulated host response to infection. "The importance of specific lipid and cholesterol metabolism genes including PCSK9, ALOX5, CETP, and DHCR7 in sepsis have been observed." (PMID 39716214, 2024). "For example, Dhcr7 mRNA has been found to be upregulated in the leukocytes of those with sepsis who have poor outcome, while inhibiting DHCR7 with AY9944 in zebrafish exposed to LPS decreased lethality." (PMID 38672427, 2024). "However, sepsis cases with increased levels of mRNA of DHCR7, GABARAPL2, MAOA, MPO, PDZD8, and TFRC had worse overall survival." (PMID 38011291, 2023). "The cholesterol metabolism gene 7-Dehydrocholesterol Reductase ( DHCR7) was significantly upregulated in both derivation and validation cohorts in poor outcome sepsis compared to rapid recovery patients and in 90-day non-survivors (validation only) and validated using RT-qPCR analysis." (PMID 36778468, 2023).
viral infections (4 papers, 2023). "Upon viral infection, macrophages reduce the expression of 7-dehydrocholesterol reductase (DHCR7, an enzyme that catalyzes 7-dehydrocholesterol [7-DHC] to cholesterol), which causes the accumulation of 7-DHC in macrophages to enhance IRF3-dependent antiviral immunity." (PMID 36750575, 2023). "First, inhibiting DHCR7 protects mice from various viral infections." (PMID 37759721, 2023). "Specifically, elevated cellular 7-DHC levels, due to deficiency of 7-DHC reductase (DHCR7) or exogenous supplementation of 7-DHC, activated PI3K/AKT3, which contributed to increased IRF3 phosphorylation and type I IFN responses upon viral infections." (PMID 36744258, 2023).